CAPN11 (calpain 11)
Description:
Calcium-regulated non-lysosomal thiol-protease which catalyzes limited proteolysis of substrates involved in cytoskeletal remodeling and signal transduction.
Synonyms: calpain11
Tractability: No criterion of Open Targets' tractability assessment is met for any kind of drug.
Gene: Protein-coding gene on chromosome 6 (44,158,811 to 44,184,401, forward strand). Ensembl gene ENSG00000137225.
Subcellular location: Cytoplasmic vesicle, secretory vesicle, acrosome
Subcellular location (Human Protein Atlas): End piece; Mid piece; Principal piece; Acrosome; Equatorial segment
Pathways (Reactome):
Extracellular matrix organization: Degradation of the extracellular matrix
Gene Ontology:
Molecular function: calcium-dependent cysteine-type endopeptidase activity; peptidase activity; calcium ion binding
Biological process: proteolysis
Cellular component: cytoplasm; acrosomal vesicle
Genetic constraint (gnomAD): Loss-of-function variants: 102 observed, 100.74 expected, observed/expected ratio (o/e) 1.01, 90% interval 0.86 to 1.19. The upper end of that interval is the gene's LOEUF score, 1.19, which puts it in group 5 of 6, group 1 being the genes least tolerant of losing a copy. Missense variants: 867 observed, 923.04 expected, observed/expected ratio (o/e) 0.94, 90% interval 0.89 to 0.99. Synonymous variants: 324 observed, 348.3 expected, observed/expected ratio (o/e) 0.93, 90% interval 0.85 to 1.02.
Homologues: Orthologues: chimpanzee CAPN11 (99% identical), rabbit CAPN11 (81% identical), pig CAPN11 (78% identical), dog CAPN11 (77% identical), mouse Capn11 (71% identical), rat Capn11 (71% identical), zebrafish capn1a (55% identical), tropical clawed frog capn11 (55% identical), guinea pig CAPN11 (54% identical), zebrafish capn1b (53% identical), Caenorhabditis elegans clp-1 (33% identical), Caenorhabditis elegans clp-7 (30% identical), and 6 more. Paralogues in human: CAPN1 (51% identical), CAPN2 (50% identical), CAPN8 (48% identical), CAPN3 (47% identical), CAPN9 (45% identical), CAPN12 (39% identical), CAPN14 (37% identical), CAPN13 (31% identical), CAPN5 (28% identical), CAPN6 (25% identical), CAPN10 (24% identical), CAPN7 (20% identical), and 8 more.
Diseases named in the same sentence as CAPN11 in open-access papers:
CAPN11 is named in the same sentence as 3 diseases in open-access papers, as found by Europe PMC text mining. Sharing a sentence is not in itself a finding about the gene and the disease. The quoted sentences say what the papers report.
tumor (2 papers, 2021 to 2023).
cancer (1 paper, 2018). A tumor composed of atypical neoplastic, often pleomorphic cells that invade other tissues. "In contrast, a small group of cancer-associated genes were up-regulated during overhaul including: Calpain 11 (Capn11), RAR-Related Orphan Receptor Gamma (Rorc), and Deoxyribonuclease II Beta (Dnase2b)." (PMID 30130361, 2018). "Importantly, overhaul exposure was associated with an up/down-regulation of 86 genes with a fold change of 1.5 or greater (p<0.5) including the immunomodulatory-linked genes S100a8 and Tnfsf9 (downregulation) and the cancer-linked genes, Capn11 and Rorc (upregulation)." (PMID 30130361, 2018).
CAPN11 also shares sentences with these, for which no sentence is quoted: Anxiety (1 paper).